NAF1 (nuclear assembly factor 1 ribonucleoprotein)
Description:
RNA-binding protein required for the maturation of box H/ACA snoRNPs complex and ribosome biogenesis. During assembly of the H/ACA snoRNPs complex, it associates with the complex and disappears during maturation of the complex and is replaced by NOLA1/GAR1 to yield mature H/ACA snoRNPs complex. Probably competes with NOLA1/GAR1 for binding with DKC1/NOLA4.
Synonyms: PFBMFT7
Tractability: PROTAC: UniProt records ubiquitination sites on it; ubiquitination databases record sites on it.
Gene: Protein-coding gene on chromosome 4 (163,110,073 to 163,166,913, reverse strand). Ensembl gene ENSG00000145414.
Subcellular location: Cytoplasm; Nucleus
Subcellular location (Human Protein Atlas): Nucleoplasm; Cytosol
Gene Ontology:
Molecular function: identical protein binding; protein binding; RNA binding; telomerase RNA binding
Biological process: positive regulation of telomere maintenance via telomerase; positive regulation of telomere maintenance via telomere lengthening; ribosome biogenesis; telomerase holoenzyme complex assembly; telomerase RNA localization to Cajal body; telomerase RNA stabilization; box H/ACA snoRNP assembly; RNA stabilization; snoRNA guided rRNA pseudouridine synthesis; pseudouridine synthesis; ribonucleoprotein complex biogenesis
Cellular component: cytoplasm; cytosol; nucleoplasm; nucleus; sno(s)RNA-containing ribonucleoprotein complex
Genetic constraint (gnomAD): Loss-of-function variants: 7 observed, 14.2 expected, observed/expected ratio (o/e) 0.49, 90% interval 0.28 to 0.93. The upper end of that interval is the gene's LOEUF score, 0.93, which puts it in group 3 of 6, group 1 being the genes least tolerant of losing a copy. Missense variants: 383 observed, 376.74 expected, observed/expected ratio (o/e) 1.02, 90% interval 0.93 to 1.11. Synonymous variants: 175 observed, 156.17 expected, observed/expected ratio (o/e) 1.12, 90% interval 0.99 to 1.27.
Gene-disease validity (ClinGen):
ClinGen rates the evidence that NAF1 causes each of these diseases.
pulmonary fibrosis and/or bone marrow failure syndrome, telomere-related, 7 (autosomal dominant): Definitive.
Homologues: Orthologues: chimpanzee NAF1 (99% identical), macaque NAF1 (96% identical), rabbit NAF1 (81% identical), guinea pig NAF1 (79% identical), dog NAF1 (75% identical), pig NAF1 (73% identical), rat Naf1 (73% identical), mouse Naf1 (72% identical), tropical clawed frog naf1 (40% identical), zebrafish naf1 (34% identical), Drosophila melanogaster CG10341 (26% identical), Caenorhabditis elegans F25H8.2 (18% identical).
Diseases named in the same sentence as NAF1 in open-access papers:
NAF1 is named in the same sentence as 38 diseases in open-access papers, as found by Europe PMC text mining. Sharing a sentence is not in itself a finding about the gene and the disease. The quoted sentences say what the papers report.
pancreatic cancer (12 papers, 2018 to 2022). "Nevertheless, the molecular mechanisms underlying the effects of resveratrol and NAF-1 and their mediation of drug resistance in pancreatic cancer remain unclear." (PMID 29765509, 2018). "To determine whether the resveratrol-induced inhibition of NAF-1 increases the susceptibility of pancreatic cancer cells to gemcitabine, we treated the Panc-1 and Mia paca-2 cells with a combination of 50 μM resveratrol and 2 μM gemcitabine, and the MTT assay was performed." (PMID 29765509, 2018). "Resveratrol increases the pancreatic cancer cells' sensitivity to gemcitabine by its effect on NAF-1 (nutrient-deprivation autophagy factor-1) and Nrf2 signaling." (PMID 34717625, 2021). "In particular, inhibition of NAF-1 expression can enhance pancreatic cancer cell sensitivity to gemcitabine, demonstrating the function of NAF-1 in the chemoresistance of pancreatic cancer cells." (PMID 33669111, 2021). "NAF-1 has been previously reported to inhibit beclin-1-dependent autophagy and promote longevity indicating that resveratrol induces autophagy during pancreatic cancer to exhibit anticancer effect." (PMID 34681206, 2021). "Resveratrol was found to inhibit the stem cell-like characteristics, migration, and invasion of pancreatic cancer both in vitro and in vivo by Nrf-2-mediated mitigation of nutrient-deprivation autophagy factor-1 (NAF-1)." (PMID 34681206, 2021). "We found that NAF-1 was significantly expressed in the five different pancreatic cancer cell lines tested, but NAF-1 was weakly expressed in CF PAC-1." (PMID 32766132, 2020). "Our study showed that the inhibition of NAF-1 can effectively inhibit the stem cell characteristics of pancreatic cancer and the invasion and the metastasis of pancreatic cancer, thereby inhibiting the progression of pancreatic cancer." (PMID 32766132, 2020). "In this study, we also found that resveratrol significantly inhibits stem cell characteristics as well as the invasion and the migration of pancreatic cancer cells by inhibiting NAF-1." (PMID 32766132, 2020). "To study the effect of NAF-1 on the invasion and the migration of pancreatic cancer cells in vitro, we first inhibited the expression of NAF-1 by shRNA in two pancreatic cancer cell lines (Panc-1 and BxPC-3)." (PMID 32766132, 2020). "This study confirmed the discovery that NAF-1 signaling plays an important role in the regulation of pancreatic cancer EMT and stem cells." (PMID 32766132, 2020). "A histopathological analysis of clinical specimens revealed that the NAF-1 expression levels are significantly increased in pancreatic cancer tissue compared with those in normal pancreatic tissue." (PMID 32766132, 2020). "To further confirm the effect of NAF-1 on the invasion ability of pancreatic cancer cells, we used a cell invasion assay to detect the invasion ability of the pancreatic cancer cell lines Panc-1 and BxPC-3." (PMID 32766132, 2020). "Based on the experimental results, we selected two pancreatic cancer cells with high NAF-1 expression, namely, Panc-1, and BxPC-3, for our subsequent experiments." (PMID 32766132, 2020). "Compared with normal pancreatic tissue, the pancreatic cancer tissue had a significantly increased expression of NAF-1." (PMID 32766132, 2020). "To elucidate the expression pattern of NAF-1 in normal and malignant pancreatic tissues, we analyzed 96 pancreatic specimens, including five normal and 91 pancreatic cancer specimens." (PMID 32766132, 2020). "In the present study, we sought to explore the role of NAF-1 and resveratrol in stem cell characteristics and to explore their contribution to the progression of pancreatic cancer." (PMID 32766132, 2020). "In a subcutaneous xenograft model of pancreatic cancer in nude mice, resveratrol inhibited the expression of NAF-1, thereby inhibiting tumor growth." (PMID 32766132, 2020). "Statistical relationship between the expression of NAF-1 and the clinicopathological features in 91 cases of pancreatic cancer." (PMID 32766132, 2020).
pancreatic cancer (continued). "The current study found that NAF-1 is expressed in pancreatic cancer tissue and correlated with the progression of pancreatic cancer." (PMID 32766132, 2020). "Taken together, our results showed that the downregulation of NAF-1 expression can reduce the stem cell characteristics of pancreatic cancer cells." (PMID 32766132, 2020). "The down-regulated NAF-1 stimulates apoptotic cell death, resulting in decreased viability and proliferation of pancreatic cancer cells." (PMID 32163546, 2020). "Our present study demonstrates that the inhibition of NAF-1 significantly inhibits the stem cell characteristics as well as the invasion and migration abilities of pancreatic cancer cells." (PMID 32766132, 2020). "At present, the molecular mechanism of NAF-1 in tumors, especially in pancreatic cancer, is still unclear." (PMID 32766132, 2020). "Through a spheroid formation assay, we found that the spheroid of pancreatic cancer cells was significantly decreased after NAF-1 inhibition." (PMID 32766132, 2020). "Our study adds to the accumulating evidence suggesting that NAF-1 can improve the chemotherapeutic sensitivity of pancreatic cancer cells and improve the clinical effectiveness of drugs." (PMID 29765509, 2018). "The resveratrol-induced ROS influence the level of NAF-1 by upregulating Nrf2, which protects the pancreatic cancer cells from the gemcitabine therapy." (PMID 29765509, 2018). "Altogether, these data suggest that the silencing of NAF-1 enhances the sensitivity of gemcitabine-resistant pancreatic cancer cells to gemcitabine." (PMID 29765509, 2018). "More importantly, decreasing the expression of NAF-1 impeded the proliferation of and activated apoptosis in pancreatic cancer cells." (PMID 29765509, 2018). "Optimistically, we further explored the role of NAF-1 as a novel molecular target for improving the efficacy of the current chemotherapeutic regimens used in patients with pancreatic cancer and improving their clinical prognosis." (PMID 29765509, 2018). "More importantly, the targeting of NAF-1 by resveratrol can improve the sensitivity of pancreatic cancer cells to gemcitabine." (PMID 29765509, 2018). "The targeting of NAF-1 via resveratrol can enhance the sensitivity of pancreatic cancer cells to gemcitabine." (PMID 29765509, 2018). "Targeting NAF-1 via resveratrol can enhance the sensitivity of pancreatic cancer cells to gemcitabine." (PMID 29765509, 2018). "Here, we demonstrate that resveratrol suppresses the expression of NAF-1 in pancreatic cancer cells by inducing cellular reactive oxygen species (ROS) accumulation and activating Nrf2 signaling." (PMID 29765509, 2018). "In this study, we found that the Nrf2 pathway and NAF-1 negatively interact with one another upon ROS stimulation, which has a crucial importance in promoting pancreatic cancer cell death." (PMID 29765509, 2018). "The immunofluorescence showed that NAF-1 is mainly localized in the cytoplasm of pancreatic cancer cells, while Nrf2 is obviously expressed in the cytoplasm and nucleus." (PMID 29765509, 2018). "The demonstrated relationship between Nrf2 and NAF-1 will further advance our understanding of the progression of pancreatic cancer induced by ROS." (PMID 29765509, 2018). "More importantly, decreasing the level of NAF-1 impeded the proliferation of pancreatic cancer cells and activated apoptosis." (PMID 29765509, 2018). "Optimistically, we further explored the role of NAF-1 as a novel molecular target for improving the efficacy of the currently used chemotherapeutic regimens in patients with pancreatic cancer and improving their clinical prognosis." (PMID 29765509, 2018). "We demonstrate that resveratrol contributes to pancreatic cancer cell death by inducing the accumulation of ROS and suppressing the expression of NAF-1." (PMID 29765509, 2018).
pancreatic cancer (continued). "Altogether, these results demonstrated that resveratrol has a potent effect in enhancing the sensitivity of pancreatic cancer cells to gemcitabine by inhibiting NAF-1 expression." (PMID 29765509, 2018). "However, the results of this study are inconsistent with the following literature: in the subcutaneous xenotransplantation model of pancreatic cancer in nude mice, resveratrol inhibits the expression of −1 (NAF-1), which inhibits autophagy." (PMID 35847371, 2022). "More importantly, resveratrol could target NAF-1 and improve the sensitivity of pancreatic cancer cells to gemcitabine." (PMID 36558995, 2022). "An experiment indicated that resveratrol could enhance the expression of NRF2 and suppress the level of nutrient-deprivation autophagy factor-1 (NAF-1), which led to cell death in pancreatic cancer cells." (PMID 36558995, 2022). "in conclusion, new drugs for reducing the transcription or activity of NAF-1 (e.g. resveratrol) may be effective in the treatment of pancreatic cancer." (PMID 34717625, 2021). "iv) In pancreatic cancer, one study found that anticancer agent resveratrol enhances the sensitivity of pancreatic cancer cells to gemcitabine via suppressing NAF-1 (nutrient-deprivation autophagy factor-1) expression, inducing ROS accumulation, and activating Nrf2 signaling pathways." (PMID 33841137, 2021). "The molecular mechanism of NAF-1 in pancreatic cancer is currently unclear." (PMID 32766132, 2020). "Interestingly, we found that resveratrol supplementation can reverse the characteristics of NAF-1 expression in pancreatic cancer." (PMID 32766132, 2020). "The other four pancreatic cancer cell lines showed a strong NAF-1 expression." (PMID 32766132, 2020). "Therefore, we conclude that resveratrol inhibited the invasion of pancreatic cancer and stem cell characteristics by inhibiting NAF-1." (PMID 32766132, 2020). "A study based on the role of resveratrol in cancer described its anticancer action in pancreatic cancer cells through suppression of the expression of NAF-1 in pancreatic cancer cells via inducing cellular reactive oxygen species (ROS) accumulation and activating Nrf2 signaling." (PMID 32660101, 2020). "Resveratrol targets NAF-1 protein in the treatment of pancreatic cancer cells." (PMID 32163546, 2020). "Furthermore, we found that NAF-1 inhibition significantly inhibits the stem cell characteristics and the invasion and migration abilities of pancreatic cancer cells." (PMID 32766132, 2020). "In this study, we found that NAF-1 is positively expressed in pancreatic cancer tissue." (PMID 32766132, 2020). "We constructed a pancreatic cancer cell line with increased NAF-1 expression using lentivirus." (PMID 32766132, 2020). "In addition, in 82/91 cases, immunohistochemical staining confirmed the widespread presence of NAF-1 staining in pancreatic cancer." (PMID 32766132, 2020). "In this study, we demonstrated that resveratrol could activate Nrf2 and suppress the expression of NAF-1 in pancreatic cancer cells by inducing the accumulation of ROS." (PMID 29765509, 2018). "In contrast, the overexpression of NAF-1 may promote the proliferation and tumorigenicity of tumors, potentially representing a novel therapeutic target for pancreatic cancer treatments." (PMID 29765509, 2018). "In addition, the knockdown of NAF-1 activates apoptosis and impedes the proliferation of pancreatic cancer cells." (PMID 29765509, 2018). "Our results showed that resveratrol could activate Nrf2 and suppress the expression NAF-1 in pancreatic cancer cells by inducing the accumulation of ROS." (PMID 29765509, 2018). "We found marked NAF-1 levels in all four pancreatic cancer cell lines, but weaker in CF pac-1." (PMID 29765509, 2018). "Moreover, NAC, which is a ROS scavenger, significantly reversed the resveratrol-induced suppression of NAF-1 and Nrf2 in the pancreatic cancer cells." (PMID 29765509, 2018).
pancreatic cancer (continued). "NAF-1 silenced by siRNA or resveratrol could enhance the sensitivity of gemcitabine in pancreatic cancer cells." (PMID 29765509, 2018). "In addition, NAF-1 expression is significantly higher in pancreatic cancer tissue than in normal pancreatic tissue, suggesting that NAF-1 may be related to the progression of pancreatic cancer." (PMID 32766132, 2020). "Therefore, a targeted molecular intervention against NAF-1 may provide a positive theoretical basis for the development of a novel treatment for pancreatic cancer in the future." (PMID 32766132, 2020). "The results in our study showed that the inhibition of NAF-1 can effectively inhibit the EMT and the stem cell characteristics of pancreatic cancer cells, suggesting that NAF-1 intervention may be an effective compound for inhibiting pancreatic cancer metastasis by targeting PCSCs and EMT." (PMID 32766132, 2020). "Therefore, we speculated that the activation of Nrf2 pathway induced by resveratrol promotes apoptosis of pancreatic cancer cells through inhibition of the downregulation of NAF-1." (PMID 29765509, 2018). "Thus, novel drug targets for inhibition of NAF-1 may be a potential therapy for preventing the progression of pancreatic cancer." (PMID 29765509, 2018). "Thus, we demonstrated that resveratrol could promote pancreatic cancer apoptosis through the ROS/Nrf2/NAF-1 pathway." (PMID 29765509, 2018). "However, the role of NAF-1 in pancreatic cancer therapy remains unknown." (PMID 29765509, 2018). "Therefore, identifying whether NAF-1 is a key signaling molecule that affects the characteristics of PCSCs and developing interventions against this key molecule may be of great significance for inhibiting the progression of pancreatic cancer and preventing resistance to chemotherapy." (PMID 32766132, 2020). "We also found that it seemed that the expression of NAF-1 was not always higher in pancreatic cancer cells." (PMID 32766132, 2020). "According to the statistical analysis of the clinicopathological results, the expression level of NAF-1 was related to the T stage of pancreatic cancer, but not to age, gender, tumor differentiation degree, or other factors." (PMID 32766132, 2020). "Resveratrol, which served as a nonspecific inhibitor of NAF-1, may exhibit greater efficacy and lower toxicity in the prevention and treatment of pancreatic cancer." (PMID 29765509, 2018). "It is worth noticing that the expression level of NAF-1 was closely related to the T stage and the TNM stage of pancreatic cancer and was not related to age, gender, tumor differentiation degree, or other factors of the patients." (PMID 32766132, 2020).